ENSG00000284695 (novel protein)
Gene: Protein-coding gene on chromosome 4 (69,810,780 to 69,847,786, reverse strand). Ensembl gene ENSG00000284695.
Genetic constraint (gnomAD): Missense variants: 78 observed, 77.28 expected, observed/expected ratio (o/e) 1.01, 90% interval 0.84 to 1.22. Synonymous variants: 29 observed, 27.45 expected, observed/expected ratio (o/e) 1.06, 90% interval 0.79 to 1.44.